RNU6-645P (RNA, U6 small nuclear 645, pseudogene)
Gene: Small nuclear RNA gene on chromosome 6 (15,324,367 to 15,324,472, reverse strand). Ensembl gene ENSG00000201519.
Homologues: Orthologues: chimpanzee U6 (96% identical), macaque U6 (95% identical), dog U6 (70% identical). Paralogues in human: RNU6-1216P (80% identical), RNU6-73P (80% identical), RNU6-1083P (79% identical), RNU6-1138P (79% identical), RNU6-1152P (79% identical), RNU6-11P (79% identical), RNU6-1243P (79% identical), RNU6-1274P (79% identical), RNU6-1310P (79% identical), RNU6-20P (79% identical), RNU6-242P (79% identical), RNU6-27P (79% identical), and 1288 more.